MTOR (mechanistic target of rapamycin kinase)
Diseases named in the same sentence as MTOR in open-access papers (continued):
Sharing a sentence is not in itself a finding about the gene and the disease.
tumor (continued). "In our previous experiments, we showed that sensitivity to mTOR inhibition in vivo correlated with tumor VEGF expression." (PMID 23533410, 2013). "A key downstream component of the PI3K pathway is the mammalian target of rapamycin (mTOR), a serine/threonine kinase involved in tumour formation and progression." (PMID 23587222, 2013). "Again, there was no statistical difference in the age of onset, sex distribution, clinical symptoms, primary lesion of the tumor, and Ann Arbor staging between p-mTOR + and p-mTOR- patients (p > 0.05)." (PMID 24112608, 2013). "One explanation for the lifespan enhancement by eRapa is that chronic mTOR inhibition delays the onset and growth of neoplasms." (PMID 23454836, 2013). "Combined therapies targeting MAPK and AKT/mTOR signaling are currently being evaluated in clinical trials for several tumor types." (PMID 23676467, 2013). "Next we investigated the effects of temporal rapamycin treatment on mTOR signaling in the tumor tissues by Western blotting." (PMID 23454868, 2013). "Rapamycin and its derivatives (rapalogs), which inhibit mTOR function by a kinase-independent mechanism, have been tested in clinical trials in several tumour types." (PMID 23434669, 2013). "Accumulating evidence now supports rapalogues potent activity against tumor blood vasculature and we have shown that mTOR inhibitors have potent anti-angiogenic effects in HNSCC." (PMID 23815869, 2013). "This same group later identified that clinically achievable doses of metformin (low μM range) were able to enhance radiation responses in vivo by blocking tumor angiogenesis and Akt-mTOR signaling, as well as enhancing apoptosis through the ATM-AMPK pathway." (PMID 24958265, 2013). "In the patient with WT, the mTOR pathway is also activated with most tumor cells showing moderate expression of p-mTOR (Ser 2448) in the plasmalemmal and cytoplasmic compartments." (PMID 23922674, 2013). "In summary, our data strongly support the idea that mTOR inhibitors induce tumor cell apoptosis in vivo by a VEGF/angiogenesis-dependent inhibitory effect." (PMID 23533410, 2013). "The mTOR pathway was activate in RCC when expression profiles of tumor and adjacent normal kidney were compared." (PMID 23349989, 2013). "The complexity of MTOR system implies contradictory functions both as tumor promoting and suppressor factors." (PMID 24244540, 2013). "Phosphoinositide 3-kinase (PI3K)/AKT/mammalian target of rapamycin inhibitor (mTOR) pathway is often constitutively activated in human tumor cells and thus has been considered as a promising drug target." (PMID 23533654, 2013). "Specifically, N-terminal fragments stimulated metastatic NEN cell line proliferation while middle fragments inhibit localized tumor cell proliferation via the AKT/mTOR pathway." (PMID 24260544, 2013). "mTOR-mediated translational signaling is important for cellular proliferation and growth in endothelial cells and various tumor cells." (PMID 23840271, 2013). "Testing AEE788 in the tumor models revealed that the combination of dovitinib + AEE788 resulted in blockade of the PI3K/Akt/mTOR pathway, prolonged tumor stasis and in the 4T1 model, a significant decrease in lung metastasis." (PMID 23343422, 2013). "mTOR inhibitors suppress autocrine and paracrine growth stimulation of tumor and lymphatic endothelial cells by impairing VEGF-C/VEGFR-3 axis and release of soluble VEGFR-2." (PMID 23815869, 2013). "By contrast, genes related to the mammalian target of rapamycin (mTOR), tumor progression, cell cycle, and metastasis/angiogenesis were down-regulated." (PMID 23587162, 2013). "The PI3K/Akt/mTOR pathway is activated in a number of human neoplasms, accompanied by lower overall and disease free survival." (PMID 23693095, 2013). "Pharmacologic mTOR inhibition has been shown to delay tumor growth and prolong survival in this model." (PMID 23641362, 2013).
tumor (continued). "One major target of p-Akt is mTOR, which is activated through p-Akt-induced direct phosphorylation and inhibition of TSC2, a tumor suppressor protein that functions as a negative regulator of mTOR." (PMID 24228033, 2013). "AMPK negatively regulates mTORC1 by (i) modulating the activity of tuberous sclerosis complex 2 (TSC2), that together with TSC1 form a tumor suppressor complex that inhibits mTOR, or (ii) through phosphorylation and inhibition of its binding partner Raptor." (PMID 24958265, 2013). "Recently, the dual PI3K/mTOR inhibitor BEZ235 has been reported to exhibit potent in vivo anti-tumor activity via inhibition of Akt and both mTOR signaling complexes." (PMID 24163230, 2013). "Rapamycin has been shown to specifically inhibit mammalian target of rapamycin (mTOR), which is a key player in tumor development and progression." (PMID 23426399, 2013). "It has been revealed that inhibition of PI3K-Akt-mTOR signaling induced cell cycle G0 and G1 arrest in tumor cells." (PMID 23432957, 2013). "The activated PI3K/PTEN/Akt/mTOR pathway has emerged as a novel contributor to HCC tumor development." (PMID 23721490, 2013). "Notably, in vitro studies propose that activation of the PIK3CA/mTOR pathway may be important in tumours with deficient homologous recombination, suggesting a possible role in gaining resistance to poly ADP ribose polymerase (PARP) inhibitors in BRCA1/2 deficient tumours." (PMID 23971979, 2013). "Based on these findings, we suspect that mTOR complex components and their interacting molecules are convergent targets of tumor-suppressive microRNAs controlled by oncogenes, such as Src and EGF." (PMID 24244675, 2013). "Further studies are warranted to validate that targeting EMMPRIN in RCC inhibits tumor angiogenesis, progression, and resistance to TKIs and mTOR inhibitors." (PMID 24073208, 2013). "Co-treatment of VPA and temsirolimus synergistically inhibited the tumor cell growth and triggered the autophagic cell death, with a significant inhibition of MTOR signaling and MYC oncoprotein." (PMID 23866964, 2013). "In DSRCT the PI3K/Akt/mTOR pathway is constitutively activated by p-Akt (Ser 473) expression in the nuclear compartment of the tumor cells and p-mTOR phosphorylated on Ser 2448, suggesting mTORC2 (rictor+mTOR) as the dominant form." (PMID 23922674, 2013). "Second, AMPK inhibits the mammalian target of rapamycin (mTOR) and the S6 kinase I pathways and this inhibition appears to be achieved by phosphorylating tuberous sclerosis complex-2, another tumor suppressor and upstream regulator of mTOR." (PMID 24100792, 2013). "The early reduction of Ktrans on DCE-MRI in orthotopic mammary xenografts following treatment with a dual PI3K/mTOR inhibitor supports the biological observation that dysregulated angiogenesis and high tumour vascular permeability are in part PI3K dependent." (PMID 22281664, 2012). "A proposed model for the inhibition of mTOR/S6K pathway occurs under hypoxic conditions through coordination of different upstream tumour suppressors." (PMID 22570651, 2012). "While mTOR inhibitors show potential in the treatment of LMS, the biology of this tumor suggests that mTOR inhibitors will be most effective when used in combination with other agents." (PMID 22448121, 2012). "Previously, constitutive activation of the PTEN/AKT/mTOR signaling axis has been firmly established as a major determinant of tumor cell growth and survival in a multitude of solid tumors." (PMID 22815832, 2012). "The Akt-mTOR pathway is an established mediator of radio-resistance and novel biological inhibitors of the two kinases are shown to sensitize tumour cells to IR." (PMID 22607554, 2012).
tumor (continued). "In human solid tumor xenografts, CQ inhibits tumor growth as a single agent in pancreatic cancer, and in combination with PI3K pathway inhibitors in glioma or with mTOR inhibitors in tuberous sclerosis complex (TSC)-deficient tumors." (PMID 22848625, 2012). "Inhibition of mTOR can decrease cancer cell proliferation and survival and reduce tumor-secreted VEGF through inhibition of hypoxia-inducible factor-1α (HIF-1α)." (PMID 21961001, 2012). "Alternatively, if autophagy activation by mTOR inhibitors promotes tumor cell survival, then therapeutic strategies to block autophagy downstream of mTOR are warranted." (PMID 22848625, 2012). "The negative regulator of autophagy, mTOR (mammalian target of rapamycin), is frequently activated and mTOR inhibitors have been shown to limit tumor proliferation in NSCLC models." (PMID 23028930, 2012). "Here we have shown that PI3K/mTOR dual inhibitors effectively block downstream targets and result in radiation sensitization in tumor cell lines and in endothelial cells." (PMID 22452803, 2012). "Recent studies have demonstrated that mTOR inhibition shows a remarkable activity against a wide range of human cancers in vitro and human tumor xenograft models." (PMID 22470194, 2012). "One recent study examining 12 GCTs showed that mTOR was expressed in every tumor sample and phosphorylated mTOR was detected in 30% of the tumor tissues." (PMID 23155381, 2012). "Taken together, our results support the idea that thioridazine targets the Akt/mTOR/p70S6K signaling pathway, which leads to the inhibition of tumor growth and metastasis." (PMID 22460505, 2012). "Consistently, tumours in which the mTOR pathway was constitutively active and/or signalling inhibited by everolimus were clinically susceptible to the drug, providing proof-of-principle." (PMID 22343617, 2012). "All patients in our study were on a treatment regimen with corticosteroids and the mTOR inhibitor rapamycin for at least a year before tumor diagnosis and excision." (PMID 22808251, 2012). "The inhibition of mTOR with its specific allosteric inhibitor, rapamycin, provokes a rapid death of squamous xenografts, resulting in tumor regression." (PMID 23185335, 2012). "The S6 phospho-specific antibody was used in order to assess the activity of mTOR/TSC upon mycotoxin-induced tumours in rats and in some human urinary tract carcinoma." (PMID 23105973, 2012). "Activation of the AKT/mTOR signalling pathways plays a role in the initiation of melanocyte tumours by modulating the extracellular signals that control cell growth, proliferation and apoptosis." (PMID 22408430, 2012). "In tumor cells ionizing radiation (IR) activates within minutes the protein kinase B (Akt) and mammalian Target of Rapamycin (mTOR) pathway leading to radio-resistance and tumor survival." (PMID 22607554, 2012). "AZD8055 and AZD2014 are pan mTOR inhibitors with potent anti-tumor activity that have been developed by AstraZenica." (PMID 23085539, 2012). "The mammalian target of rapamycin (mTOR), a key player in cell growth and tumor development located downstream in the Akt signaling pathway, was activated in Env-induced lung tumors of both C57BL/6 and NOD/SCID mice." (PMID 23251519, 2012). "Recent studies have reproted that GOLPH3 works as an oncoprotein promoting cell transformation and tumor growth by enhancing the activity of mTOR." (PMID 23006319, 2012). "In the current study utilising 167 OSCC samples, about 70% of the OSCC tumours showed p-mTOR (i.e., mTOR activation)." (PMID 22333597, 2012). "The treatment of rapamycin (a mTOR inhibitor) and siRNA-mediated mTOR knockdown inhibit tumor cell invasion as well as the secretions of MMP-2 and uPA." (PMID 23226337, 2012).
tumor (continued). "Here, we show the degree to which RAD001 and BEZ235 can be synergistically combined to inhibit mTOR pathway activation, cell proliferation and tumor growth, both in vitro and in vivo." (PMID 23155392, 2012). "Other studies have shown that radiation induces activation of mTOR pathways in the tumor endothelial cells making them more sensitive to response with rapamycin." (PMID 23185335, 2012). "Synergistic responses between sorafenib and mTOR inhibitors were observed in xenograft studies with a highly metastatic human HCC tumor." (PMID 23085539, 2012). "Everolimus, an oral mTOR inhibitor, has shown particularly promising results in experimental studies, inhibiting tumour growth and displaying anti-angiogenic effects." (PMID 22333597, 2012). "First, most OSCC tumours were positive for p-mTOR expression, supporting a role for mTOR activation in the pathogenesis of OSCC." (PMID 22333597, 2012). "Both compounds effectively inhibited phosphorylation of Akt, mTOR and S6 target proteins and reduced clonogenic survival in irradiated tumor cells." (PMID 22452803, 2012). "Mutations resulting in activation of the Ras/PI3K/PTEN/Akt/mTOR pathways and play critical roles in EMT, tumor progression and aging." (PMID 23006971, 2012). "Dual PI3K/mTOR inhibitors have demonstrated significant, concentration-dependent cell proliferation inhibition and induction of apoptosis in a broad panel of tumor cell lines, including those harboring PIK3CA activating mutations." (PMID 23085539, 2012). "Treatment with the dual PI3K/mTOR inhibitor BEZ235 produced a minimal tumor response that increased dramatically when BEZ235 was combined with doxorubicin." (PMID 22619567, 2012). "The mammalian target of rapamycin (mTOR) is a key regulator of cell growth, proliferation and cellular metabolism, and is activated downstream of several oncogenes and tumor suppressors." (PMID 23155392, 2012). "These mTOR inhibitors show anti-tumor properties in vitro, in vivo and the ability to improve sensitivity to chemotherapeutic agents." (PMID 23372575, 2012). "Further investigation is warranted in a subpopulation with tumours in which mTOR signalling is constitutively activated, characterised by high expression of pS6Ser240/4." (PMID 22343617, 2012). "mTOR plays a key role in the regulation of cell cycle progression, which includes protein synthesis, tumor growth, and angiogenesis." (PMID 22460505, 2012). "PI3K/Akt/mTOR inhibitors will sensitize the tumor vasculature to radiation both in vitro in cell lines and in vivo in xenografts." (PMID 23085539, 2012). "The analysis of the tumors subjected to each treatment revealed that ATP-competitive inhibitors of mTOR and U0126 reduced tumor cell proliferation as evidenced by decreased levels of Ki-67 staining." (PMID 22401294, 2012). "The lack of routine genotyping of tumours is also part of the limitations in establishing predictive biomarkers for the use of mTOR inhibitors across the spectrum of human tumours." (PMID 22408430, 2012). "The high percentage of p-mTOR-positive tumours supports the crucial role of mTOR activation in the pathogenesis of OSCC." (PMID 22333597, 2012). "The MTOR expression level in tumor tissues was significantly higher than that in the adjacent normal tissues (P = 0.018)." (PMID 23209702, 2012). "Palomid 529 (Paloma Pharmaceuticals) is a pan mTOR inhibitor which has potent anti-tumor affects and reduces tumor angiogenesis and vascular permeability." (PMID 23085539, 2012). "PI3K/Akt in turn regulates tumor growth and angiogenesis through downstream targets, mTOR, p70S6K1, HIF-1, and VEGF." (PMID 22505939, 2012). "In epidemiological studies, switching from an immunosuppressive therapy with calcineurin inhibitors to the mTOR-inhibitor sirolimus was effective to reduce skin carcinogenesis in renal transplant patients by 50%." (PMID 22808251, 2012).
tumor (continued). "So far and for most tumour types, mTOR inhibitors have been reported to predominantly lead to disease stabilization rather than tumour regression." (PMID 22408430, 2012). "Dysregulation of mTOR pathway has been found in many human tumours; therefore, the mTOR pathway is considered an important target for the development of new anticancer drugs." (PMID 23094058, 2012). "The mammalian target of rapamycin (mTOR) has been identified as a key player in tumor growth, metastasis and angiogenesis." (PMID 23094058, 2012). "Due to the vital role of PTEN/AKT/mTOR axis in tumor pathophysiology, emerging research on the axis concern its potential as a target of rationally molecular anticancer therapies." (PMID 22815832, 2012). "DEPDC6 (DEP domain-containing mTOR-interacting protein or DEPTOR) is a negative regulator of mTOR signaling and is therefore expected to be a tumor suppressor." (PMID 23213280, 2012). "Quercetin dramatically inhibited the phosphorylation of AKT, mTOR, and P70S6K, but the total protein levels remain unchanged, indicating that the AKT/mTOR pathway is also a possible target of quercetin in tumor cells." (PMID 23094058, 2012). "The phosphatidylinositol 3-kinase (PI3K)/Akt/mammalian target of rapamycin (mTOR) pathway controls tumor cell proliferation, growth, and survival after DNA damage." (PMID 22452803, 2012). "Akt-mTOR signaling is a critical pathway driving tumor initiation in the Apcmin/+ mouse, since it promotes cell cycle progression through posttranscriptional control of the key cell cycle regulators, such as Cyclin D1, cyclin E, and c-Mycand LOH of Apc." (PMID 23112799, 2012). "Combined inhibition of EWS-FLI1 (oligonucleotide) and EWS-FLI1-modulated pathways (e.g., mTOR) increased the antitumour effect (apoptosis, in vivo tumour regression)." (PMID 23226965, 2012). "Rapamycin and novel analogue molecules, so-called Rapalogs, represent one class of putative tumor therapeutics which act by inhibiting protein synthesis via the mammalian target of rapamycin, mTOR." (PMID 22619676, 2012). "Our past work and that of others point to increased PI3K/Akt/mTOR signalling as a mediator of enhanced tumor survival after radiation-induced DNA damage." (PMID 22452803, 2012). "Activation of Akt also promotes tumor metastasis and invasion, antagonizes cell-cycle arrest, angiogenesis, and phosphorylates mTOR (mammalian target of rapamycin) protein kinase." (PMID 22460505, 2012). "A recent study that examined the distinct downstream transcriptional programs of mTOR in a tumor model has pinpointed mTOR as a determinant in effector versus memory CD8+ T cell fate." (PMID 23028309, 2012). "It follows that inhibitors of mTOR, such as rapamycin and its derivatives are currently being evaluated for molecular targeted therapy of neoplastic diseases." (PMID 23185335, 2012). "Two previous reports and this current study illustrate that RAD001 and BEZ235 can be combined to synergistically inhibit mTOR signaling and tumor growth." (PMID 23155392, 2012). "Phosphorylated S6 ribosomal protein is a marker for the activity of mTOR and it was found that the level of phosphorylated S6 ribosomal protein expression was predictive of early tumor response to the mTOR inhibitor." (PMID 22709827, 2012). "It was recently reported that IKKβ increased tumor development and tumor angiogenesis by activating the mTOR signaling pathway through inhibiting tuberous sclerosis 1 (TSC1)." (PMID 22848663, 2012). "The phosphatidylinositol-3-kinase (PI3K-PKB), mitogen activated protein kinase (MEK-ERK) and the mammalian target of rapamycin (mTOR- p70S6K), are thought to regulate many aspects of tumour cell proliferation and survival." (PMID 22475322, 2012).